AQP4 (aquaporin 4)
Diseases named in the same sentence as AQP4 in open-access papers (continued):
Sharing a sentence is not in itself a finding about the gene and the disease.
glioma (continued). "Our histological results were consistent with previous studies that the AQP1, AQP4 and Ki-67 expression were significantly increased in the high-grade gliomas compared with the low-grade gliomas." (PMID 34712604, 2021). "Another reported mechanism, which contributes to migration, is the expression of aquaporin 4 (AQP4) observed in glioma cells after Kyn/AhR interaction." (PMID 34071442, 2021). "Lower levels of a small non-coding RNA miRNA-320a in gliomas were correlated with poor prognoses; conversely, miRNA-320a overexpression in U87MG and U251MG cell lines was associated with decreased levels of AQP4 and decreased migration and invasion." (PMID 34769339, 2021). "Our most recent review has confirmed that AQP4 is highly expressed in glioma tissues, and AQP4 exerted carcinogenic effects via various pathways in glioma." (PMID 34113257, 2021). "Further studies are needed to establish the role of the ALPS index as an imaging marker of AQP4 expression in gliomas." (PMID 34631582, 2021). "The protein kinase-C (PKC) activator phorbol 12-myristate 13-acetate (PMA) suppresses migration and adhesion in glioma cells in vitro, and reduces AQP4–mediated water permeability." (PMID 34769339, 2021). "AQP4 was also reported to have higher expression in both tumor and peritumor than in normal tissues in gliomas, but the degree of peritumoral edema only positively correlates with the expression level of AQP4 in peritumor." (PMID 34712604, 2021). "It is of interest to determine the potential value of AQP4 in identifying, guiding treatment and prognosticating various types of CNS cancers." (PMID 34113257, 2021). "We also explored gene expression and alteration, signaling pathways, immune infiltration, protein phosphorylation and overall patient survival to characterize the nature of AQP4 in the biology and clinical prognosis in patients with CNS cancers." (PMID 34113257, 2021). "Our study further clarified the potential therapeutic effect of AQP4 in CNS cancers and its immune-related biological mechanisms." (PMID 34113257, 2021). "The expression levels of IDO1, TDO, AhR, and AQP4 in the tumor areas of GL261 orthotopic glioma mice were higher than those in the corresponding brain tissue from healthy mice." (PMID 32296044, 2020). "Using rabies virus glycoprotein–modified exosomes, delivery of miR-383-5p inhibited the expression of AQP4 not only in rat C6 glioma cells in vitro but also in the hippocampus in vivo." (PMID 33013433, 2020). "In the present study, we identified that AQP4 served as a downstream target for miR-216a and confirmed that LINC00461/miR-216a axis regulated glioma cell proliferation, apoptosis, migration, and invasion depending on modulating AQP4 expression." (PMID 33817241, 2020). "AQP4 plays an important role in the anti‐glioma effect of TMZ; however, the exact mechanisms still need more research." (PMID 31746080, 2020). "In this study, we further elucidated the therapeutic effect of AQP4 in malignant glioma and its molecular mechanism in anti‐glioma treatments." (PMID 31746080, 2020). "AQP4 was significantly upregulated in glioblastoma multiforme (IV stage) compared to low-grade glioma." (PMID 33817241, 2020). "The close involvement of AQP4 in cell migration and invasion was summarized in glioma malignancy, as well as drug resistance." (PMID 33817241, 2020). "Upregulation of AQP1 and AQP4 protein and RNA has been the major focus of papers published in the glioma field, with additional work identifying possible involvement of AQP9." (PMID 32679804, 2020). "Our work suggested LINC00461/miR-216a/AQP4 circuit as a novel pathway in the occurrence and development of glioma." (PMID 33817241, 2020). "However, the association between miRNAs and AQP4 remains unclear in glioma except one." (PMID 33817241, 2020). "More specifically, AQP4 is frequently expressed in GBM and it is widely accepted that an increased expression is associated with glioma invasion and migration." (PMID 32160197, 2020).
glioma (continued). "This study demonstrated that IR upregulates AQP1 and AQP4 in GSC glioma tissue and 83NS cells in vitro." (PMID 31803626, 2019). "A role for AQP4 in glioma cell migration has similarly been proposed to occur through regulation of cell volume and cytoskeletal interactions." (PMID 29922644, 2018). "Protein kinase C (PKC)-mediated phosphorylation of AQP4 at serine 180 correlated with a decreased glioma cell invasion." (PMID 29922644, 2018). "In glioma, AQP4 levels correlated with migration and invasiveness in vitro and in vivo through a mechanism involving MMP2." (PMID 29922644, 2018). "AQP4 has been demonstrated as a significant factor in glioma malignancies regulating invasion, migration of gliomas and edema formation." (PMID 30555637, 2018). "In human glioma and primary astrocytes, reduced AQP4 expression correlated with dramatic morphological elongation, reduced invasiveness, and impaired F-actin polymerization." (PMID 29922644, 2018). "Aside from water transport, AQP4 has been shown to contribute to the regulation, invasion and migration of gliomas." (PMID 28423683, 2017). "This further confirms previous reports regarding the redistribution of AQP4 with the increase of the glioma grade." (PMID 28423683, 2017). "Currently, the effect of AQP4 in promoting glioma cell migration and invasion can be summarized by the results of several key studies." (PMID 28423683, 2017). "The miR-5096 inhibitor slightly decreased, while miR-5096 mimic slightly increased, AQP-4 expression in glioma cells." (PMID 28445150, 2017). "The molecular mechanism of AQP4 as it pertains to the migration and invasion of human glioma cells has been summarized." (PMID 28423683, 2017). "AQP4 is dissociated from the OAPs and redistributes across the entire surface of glioma cells under tumor conditions." (PMID 28423683, 2017). "Aside from water transport, other potential roles of AQP4 in the regulation, invasion and migration of gliomas have been slowly elucidated." (PMID 28423683, 2017). "Cell cultures of murine astrocytes from healthy brain and human glioma cells (TuGlio 25 and U373) were processed for qRT-PCR to compare their expression of AQP4 isoforms to the patients’ tumor tissue." (PMID 27483250, 2016). "Our previous studies have shown that the expression of AQP4 in glioma cells and its morphological appearance depend on the environmental milieu, especially on components of the extracellular matrix (ECM) of the brain region itself, or within the tumor." (PMID 26115524, 2015). "In gliomas, aquaporin-4 is upregulated, and this upregulation is thought to result in increased migration/invasion as well as contributing to tissue edema." (PMID 24465609, 2014). "Our previous study also showed that reduction of AQP4 induced impaired migration and invasion of human glioma cells." (PMID 23950863, 2013). "The results of this study indicate that AQP4 expression of grafted glioma cells depends on the surrounding microenvironment." (PMID 22590566, 2012). "They compared the expression of several molecules of the neurovascular unit, including AQP4, inside and outside the grafted glioma." (PMID 22590566, 2012). "In contrast, most cultivated glioma cell lines don’t express AQP4, and primary cell cultures of human glioblastoma lose it during the first passages." (PMID 22590566, 2012). "AQP4 expression has been reported in a series of brain tumors such as glioma, glioblastoma and astrocytoma." (PMID 22808259, 2012). "Taken together, AQP4 expression were observed in most proliferating glioma cells and the knockout of AQP4 could largely slow down proliferation activity, suggesting AQP4 is the potential molecule connecting MRI-kio with proliferation activity." (PMID 40225573, 2025).
glioma (continued). "For example, TGN-020, a selective AQP4 inhibitor, has demonstrated efficacy in reducing cerebral edema and glioma cell migration in animal models, while AER-271, a more recent compound, has shown similar effects with improved pharmacokinetics and CNS penetration." (PMID 41324079, 2025). "Molecular docking studies revealed the specific bioactive mechanisms of each fraction: CMP1 exerted immunomodulatory effects by interacting with TLR4 and DC-SIGN receptors and exhibited therapeutic potential for brain edema or glioma via targeted binding to AQP4." (PMID 41155515, 2025). "The negative correlation between MRI-kbo and Ki67+ could potentially result from the redistribution of AQP4 from perivascular astrocytic end-feet to the cell membrane in gliomas 26,27." (PMID 40225573, 2025). "Upregulated AQP4 expression were observed in most proliferating glioma cells and the knockout of AQP4 could largely slow down proliferation activity, suggesting AQP4 is the potential molecule connecting MRI-kio with proliferation activity." (PMID 40225573, 2025). "Thus, The Kyn–AhR axis also influences AQP4 expression by favoring the upregulation of the M1-AQP4 isoform, thus reinforcing the pro-invasive and therapy-resistant phenotype of glioma cells." (PMID 41324079, 2025). "AQP4 dysfunction—particularly its isoform-specific expression and subcellular mislocalization—emerges as a converging mechanism linking glymphatic system disruption with glioma progression." (PMID 41324079, 2025). "Numerous case reports have underscored the diagnostic challenges and occasional clinical overlap between NMOSD and gliomas, primarily due to the risk of misdiagnosis in which often NMOSD is erroneously identified as brain tumors located in regions where AQP4 is abundantly expressed." (PMID 41324079, 2025). "This paradoxical outcome suggests a potential immunological conflict between active NMOSD and glioblastoma progression, reinforcing the notion that AQP4-targeted autoimmunity could inherently oppose glioma advancement." (PMID 41324079, 2025). "Systematic reviews and large multicenter patient registries could provide crucial insights into whether NMOSD offers any protective effect against glioma development and whether AQP4-targeted immunity could be therapeutically exploited." (PMID 41324079, 2025). "Furthermore, these TCEs enhanced the invasion and migration of glioma cells by promoting the expression of AQP4 via the kynurenine/AHR signalling pathway." (PMID 40071723, 2025). "Thus, the relative abundance and distribution of AQP4 isoforms can influence the invasive phenotype of glioma cells." (PMID 41324079, 2025). "Given its potential role in glioma progression and the tumor immunosuppressive microenvironment, further investigation into the mechanisms of AQP4 may provide novel therapeutic insights for glioma treatment." (PMID 40788933, 2025). "Upregulated aquaporin 4 (AQP4) expression were observed in most proliferating glioma cells and the knockout of AQP4 could largely slow down proliferation activity, suggesting AQP4 is the potential molecule connecting MRI-kio with proliferation activity." (PMID 40225573, 2025). "AQP4, a major water channel protein, plays a key role in glioma development, and abnormal upregulation of AQP4 expression may serve as an indicator of glioma, facilitating glioma infiltration into the brain." (PMID 38954698, 2024). "Furthermore, AQP4 deletion obstructed glioma cell motility and F-actin polymerization, both of which are essential in cell-cell adhesion." (PMID 38336645, 2024). "The fascinating finding of AQP4 protein up-regulated combined with OAPs down-regulated may explain the M1 isoform up-regulation in gliomas." (PMID 39247976, 2024). "This discovery is in agreement with our results showing overexpression of AQP4 genes in gliomas, placing aquaporin 4 as an important biomarker to be used both in bioinformatics analyzes and in brain imaging as a potential therapeutic treatment of gliomas." (PMID 38476871, 2024).
glioma (continued). "Studies have demonstrated that cells in glioma exhibit significant AQP4 staining throughout." (PMID 39247976, 2024). "Overview of potential AQP4 modulators for possible use in glioma treatment." (PMID 39247976, 2024). "In addition, both AQP1 and AQP4 showed a significant difference in expression pattern upon comparison with tumor markers/antigens in gliomas that are consensually used in clinical practice to establish degrees of malignancy and prognosis." (PMID 38476871, 2024). "The researchers observed that all glioma patient biopsies expressed AQP4." (PMID 39200356, 2024). "The particular roles of the M1 and M23 isoforms of AQP4 in glioma development have been identified." (PMID 39247976, 2024). "According to earlier studies, CS-6 decreased the expression of AQP4 protein in glioma cells." (PMID 39247976, 2024). "Due to the role of KATP channels in proliferation and apoptotic outcomes in gliomas, we tested the hypothesis that Kir6.2-SUR2 and AQP4 collaborate in glioma cell apoptotic fate." (PMID 39200356, 2024). "Thereafter we discuss some possible mechanisms of action of AQP4 translocations in glioma." (PMID 39247976, 2024). "The molecular pathways and AQP1 and AQP4 genes identified here may be useful for the molecular diagnosis of gliomas and for screening new anti-tumor drugs for these malignant tumors." (PMID 38476871, 2024). "Different membrane dynamics displayed by each AQP4 isoform could assist in understanding how AQP4 gets dysregulated in gliomas." (PMID 39247976, 2024). "The redistribution of AQP4 sub-cellularly in gliomas may be greatly influenced by the modulation of AQP4 isoform expressions." (PMID 39247976, 2024). "We can speculate that Kir6.2 upregulation in AQP4-OAP-expressing cells is helpful to glioma cells, helping them to escape from apoptosis and survive." (PMID 39200356, 2024). "We identified the crucial role that AQP4 plays in the immune microenvironment of malignant gliomas, suggesting that AQP4 has the potential to be a breakpoint in malignant glioma for future discovery of the immune microenvironment of glioma." (PMID 36599974, 2023). "In addition to osmotic pressure, hypoxia is an important factor affecting aquaporin 4 regulation in relation to gliomas." (PMID 37893105, 2023). "Due to its pivotal role in the glymphatic system, AQP4 may contribute to the impact on glioma malignancy." (PMID 36599974, 2023). "We further compared AQP4 expression levels between tumor and normal brain tissues of LGG and GBM, respectively, and found that AQP4 tends to be overexpressed in the tumor samples (p < 0.05), inferring that AQP4 may have an impact on glioma development." (PMID 36599974, 2023). "Reduced AQP4 expression with glioma has been demonstrated in a recent study." (PMID 37904254, 2023). "Glioma cells show dysregulated expression and disordered localization of AQP4, which is expressed as a non-OAP-associated form throughout the astrocytic membrane rather than restricted to the OAPs in the glial endfoot membranes." (PMID 36768856, 2023). "Compared to the low AQP4 group, the high AQP4 group tended to have shorter OS in all gliomas." (PMID 36599974, 2023). "As AQP4 water channels form part of the glymphatic system, we hypothesize that there may be a correlation between ALPS index values and expression of AQP4 water channels and expression levels in gliomas." (PMID 37508938, 2023). "Evidence showing a correlation between peritumoral brain edema and elevated AQP4 expression levels in human gliomas astrocytes indicates that increased expression could play a key role in its pathogenesis." (PMID 37508938, 2023). "Correspondingly, overexpression of VEGF in gliomas induces upregulation of AQP4 mRNA expression." (PMID 35910247, 2022). "The role of AQP4 in the occurrence and development of glioma is still unclear." (PMID 36523816, 2022).
glioma (continued). "The results of this study have a significant reference value for the prognosis research of AQP4-related glioma patients, and have indicated that AQP4 could be considered as a potential new early biomarker of glioma progression." (PMID 36523816, 2022). "Furthermore, more in-depth explorations should be done to elucidate the roles of AQP4 protein relocalization in glioma in our future research." (PMID 36523816, 2022). "Therefore, this study further explored the role of AQP4 in the immune regulation of glioma and the process of immunotherapy." (PMID 36523816, 2022). "Current research provides a novel, vital AQP4-related immune status and prognostic model in glioma." (PMID 36523816, 2022). "The results show that EVs generated from GBM cells expressing AQP4-tetramers potentiate the invasiveness ability of recipient cells, while EVs generated from GBM cells expressing AQP4-OAPs favour their apoptotic path, indicating AQP4 as an important cargo in EV mediated communication in glioma." (PMID 36071478, 2022). "Interestingly, even though glioma tissue shows upregulated AQP4 expression, the expression levels of AQP4-OAPs remain unchanged." (PMID 35910247, 2022). "Overall, these data demonstrated the prognostic significance of AQP4 in glioma." (PMID 36523816, 2022). "More intriguingly, current research has indicated that AQP4 protein aggregation state could be a determinant for glioma cell fate, strengthening the potential role of AQP4 as a target in the treatment of GBM." (PMID 36523816, 2022). "More recently, the dynamics of AQP4 aggregation/disaggregation into OAPs and their link with the actin cytoskeleton were found to be determinants in glioma cell fate through altering plasma membrane dynamics to influence cell proliferation, cell migration and apoptotic potential." (PMID 36010640, 2022). "It is widely accepted that increased expression of AQP4 in GBM cells is also associated with glioma invasion and migration, but recent data do not support any prognostic role of this marker in GBM." (PMID 36295510, 2022). "Finally, miR-320a has been reported to impede glioma cell invasion and migration by targeting aquaporin 4 (AQP4), which was recently defined as a strong regulator of cell invasion and migration in glioma subjects." (PMID 35922753, 2022). "We believe that this study adds knowledge on the complex role of AQP4, different from its well-known primary function of the plasma membrane water channel in tumour biology and in the pathophysiology of glioma providing information on regulating the EV-mediated pro-tumorigenic response." (PMID 36071478, 2022). "The possibility that AQP4 protein could be released by glioma cells in a tumour microenvironment was first investigated." (PMID 36071478, 2022). "All these suggest the involvement of AQP4 in malignant brain tumors and indicated that AQP4 could serve as a potential target for therapy of glioma." (PMID 34113257, 2021). "In recent years, a new function of AQP4 has been described, specifically its role in the inflammatory response, mediating the migration of immune cells, edema, and as a marker of poor prognosis in gliomas." (PMID 34068922, 2021). "In addition, mean kurtosis, as one potential DWI metric measuring the degree of diffusion hindrance or restriction, has been reported to correlate with AQP4 expression in gliomas." (PMID 34712604, 2021). "AQP4 redistribution is a common phenomenon in glial tumors, including glioblastoma." (PMID 34082828, 2021). "It is noteworthy to consider an antibody-based approach in conditions where AQP4 function (as cytotoxic edema, ocular neovascularization, and astroglia proliferation including glial scarring and infiltration of glial tumors) is related to exacerbation or propagation of pathologic conditions." (PMID 34966347, 2021). "Other authors link AQP4 to the regulation of human glioma cells migration and invasion." (PMID 34113257, 2021).